CD4 (CD4 molecule)
Diseases named in the same sentence as CD4 in open-access papers (continued):
Sharing a sentence is not in itself a finding about the gene and the disease.
type 2 diabetes (continued). "Our data also show that lack of susceptibility to suppression is a type 2 diabetes-specific feature of VAT-derived CD4 and CD8 T cells." (PMID 32299896, 2020). "Patients with overt type 2 diabetes might show higher population of senescent CD4+ and CD8+ T cells in PBMCs compared with normal controls." (PMID 30867412, 2019). "When B cells were congenitally deficient, HFD-fed obese mice did not develop type 2 diabetes, their fasting sugar, and insulin tolerance tests were unaffected, but helper CD4 T cell function was ameliorated." (PMID 31998318, 2019). "It is also possible that changes in the population of senescent CD4+ T cells may follow the functional changes of senescent CD4+ T cells in the development of type 2 diabetes in humans." (PMID 30867412, 2019). "These hereditary issues result in an imbalance in CD4+T cells and a decreased level of naïve CD4+T cells, which may be critical in the pathogenesis of type 2 diabetes." (PMID 30044774, 2018). "More importantly, in the same study, there was a significant increase in the infiltration of renal interstitial T (CD4+, CD8+) and B cells (CD20+) in type 2 diabetic human kidney, and the increase in CD4+ T cells and CD20+ B cell correlated with the amount of proteinuria in these patients." (PMID 29910771, 2018). "Previous clinical studies found that plasma levels of IL-22 and the number of IL-22-producing CD4+ T cells were higher in insulin-resistant or type 2 diabetic obese individuals than in insulin-sensitive obese or lean individuals, but results were based on very small samples." (PMID 28143481, 2017). "Consistent with this hypothesis, adjusting for CMV and H. pylori, correlates of CD4+ memory and naive cell subpopulations in MESA, reduced the associations of %memory with type 2 diabetes." (PMID 26458065, 2015). "Relationships of higher memory and lower naive CD4+ T cells with type 2 diabetes may reflect both direct and/or indirect mechanisms." (PMID 26458065, 2015). "Notably, CD4 count < 100/μl provided the highest sensitivity (0.93, 95% CI 0.79 – 0.98; specificity 0.49) while coma provided the highest specificity (0.84, 95% CI 0.76 – 0.90; sensitivity 0.37)." (PMID 17493266, 2007). "Work in progress involves connecting the present macrophage network with a CD4 T cell lymphocyte differentiation network with the aim of simulating the immune response to respiratory infections, and that of diseases with chronic inflammatory origin, such as type 2 diabetes." (PMID 41550924, 2025). "Given that an impaired CD4+T cell differentiation was detected after the first dose of BNT162b2 vaccination, it is possible that the poor vaccine efficacy with CoronaVac among patients with type 2 diabetes is also related to a compromised initial CD4+T cell response." (PMID 36304475, 2022). "T2D has known imbalances of CD4+T cells and decreased levels of naïve CD4+T cells, which in turn play an important role in the pathogenesis of type 2 diabetes." (PMID 30044774, 2018). "Compared with healthy subjects, lower expressions of PD-1 on monocytes, CD4+ T cells, and CD8+ T cells were identified in patients with type 2 diabetes." (PMID 39518420, 2024). "Studies have demonstrated that immune cells, especially circulating CD4+ T helper cells, are important source of plasma DPP4 activity which is responsible for postprandial glucose intolerance in patients with type 2 diabetes." (PMID 35309368, 2022). "In contrast to the S-reactive CD4+T cell responses, the proportions of S1- and S2-reactive CD8+ T cells in HCs and type 2 diabetes were comparable following both doses of vaccination." (PMID 36304475, 2022). "Changes in peripheral blood T-lymphocyte subsets in type 2 diabetes were manifested as decreased CD3+ T cells, CD4+ T cells, and CD4+/CD8+ T cell ratio and increased or decreased CD8+ T cells." (PMID 34568395, 2021).
type 2 diabetes (continued). "In conclusion, traditional Chinese medicine GAG, which effectively treats type 2 diabetes in clinic, can also alleviate autoimmune T1DM in NOD mice by upregulating both CD4+FoxP3+ and CD8+CD122+PD1+ Tregs." (PMID 28947964, 2017). "The significant difference observed in CD4+ T cell counts between the groups highlights the immunological compromise in the ART and ART + type II diabetes groups compared to the control, reflecting the chronic immune activation and viral burden associated with HIV infection." (PMID 39860995, 2025). "Abnormal expression of the NKG2D receptor has been observed in CD4+ T cells in patients with type 2 diabetes, particularly in a subset of CD4+CD28− T cells, which are more abundant compared to non-diabetic patients." (PMID 41301424, 2025). "Additionally, MDSCs can suppress the activity of CD4+ and CD8+ T cells, thereby preventing the development of type 2 diabetes." (PMID 39518420, 2024). "Furthermore, our observations indicate a reduction of PD-1+ CD4 Tconv cells in VAT of obese patients with dysglycemic and an augmentation in the liver of individuals with NASH and type 2 diabetes." (PMID 38380252, 2024). "Similar to CD4+T cell memory responses, the proportions of participants bearing S-reactive CD8+T cells and the frequencies of cytokine-producing and cytotoxic CD8+T cells among the responders were comparable between HCs and participants with type 2 diabetes." (PMID 36304475, 2022). "However, in contrast to the findings with CD4+TSCM, comparable level of S1-reactive CD8+TSCM was detected in HCs and participants with type 2 diabetes after both doses." (PMID 36304475, 2022). "However, the frequencies of effector CD4+ T cells, regulatory T cells, and B cells increased, suggesting a decrease of proinflammatory cellular immunity in nonpregnant type 2 diabetic patients treated with insulin, as compared to control subjects." (PMID 32626786, 2020). "Moreover, similar frequencies of CD4+T cells that produced individual cytokines or co-produced TNFα and IFNγ following S1 or S2 peptide stimulation were detected in responders with or without type 2 diabetes." (PMID 36304475, 2022). "Our findings demonstrated that mRNA vaccine (BNT162b2) effectively induced antigen-specific CD4+ and CD8+ memory T cells, as well as anti-RBD IgGs and neutralizing antibodies in all vaccinees regardless of the presence of type 2 diabetes." (PMID 36304475, 2022). "CD4 and CD8 T cells from PB of the overall obese population (ie, non-diabetic obese and obese patients with type 2 diabetes) showed a similar level of proliferation/activation on in vitro stimulation compared with LC (data not shown)." (PMID 32299896, 2020). "The aim of this study was to examine the fluctuations in CD4+ T cells, CD8+ T cells, and natural CD4+CD25+FoxP3+T-regulatory (Treg) cells following an oral glucose tolerance test (OGTT) in participants with and those without type 2 diabetes (T2DM)." (PMID 29615971, 2018).
atopic dermatitis (100 papers, 2008 to 2026). "Normal and filaggrin(FLG)-deficient (predisposing factor for atopic dermatitis) hPSkCs were cultured on top of naïve human CD4+ T cells." (PMID 38136325, 2023). "Atopic dermatitis showed significant associations with a number of cell types, including the T helper 1 cell, CD4-positive alpha–beta T cell, CD4-positive helper T cell, T cell, inflammatory macrophage, and the regulatory T cell, all of which are immune cells." (PMID 36232752, 2022). "In dogs, CD4+/CD8+ cells are critical against parasite proliferation; both demodex and atopic dermatitis are associated with CD4+/CD8+ cells." (PMID 36009627, 2022). "Recently, miR-155 was shown to be overexpressed in tissues of patients with atopic dermatitis, associated with inflammatory CD4+ T cells and capable of targeting CTLA-4." (PMID 25090912, 2014). "Besides that, the CD4+ T cell showed a risk causal effect on PA (OR = 3.92, p = 2.74 × 10–4) and the ratio of CD4+ T/CD8+ T also had a risk effect on atopic dermatitis (OR = 2.33, p = 4.70 × 10–2)." (PMID 38263182, 2024). "MiR-155 overexpression in human CD4+ T cells promoted proliferation, and could underlie chronic inflammation in atopic dermatitis, in which it is highly expressed also by CD4+ T cells present in skin lesions." (PMID 30319616, 2018). "Mite allergens result in localized allergic dermatitis characterized by pronounced epidermal hyperplasia and spongiosis, which was associated with infiltration of eosinophils, neutrophils, degranulated mast cells, CD4+ and CD8+ T cells, and dendritic cells." (PMID 28460633, 2017). "In addition, severe atopic dermatitis is associated with reduced frequency of IL-10-producing allergen-specific CD4+ T cells." (PMID 22968402, 2012). "Additionally, L. acidophilus DDS-1, in combination with B. lactis UABla-12, displayed improved symptomology associated with atopic dermatitis in a randomized controlled trial, with modulation of blood lymphocyte subsets (i.e., CD4, CD8 and CD25) suggesting an immune regulatory role." (PMID 32019158, 2020). "Like atopic dermatitis, the dermal lymphocytic infiltrate in OS is dominated by CD4 + T-cells, with a reported CD4/CD8 ratio of 4:1." (PMID 38433167, 2024). "In atopic dermatitis mice, CD4+RORγt+ Th17 cell numbers in lymph nodes increased, which was reversed by magnolol treatments." (PMID 38541664, 2024). "Previous studies utilizing PBMCs, CD4 T cells, and primary Th17 cell clones derived from patients with atopic dermatitis have demonstrated that α-hemolysin induces IL-17 release." (PMID 39240270, 2024). "Flow cytometry determined the proportion of CD4+RORγt+ Th17 cells and CD4+FoxP3+ Treg cells in cervical lymph nodes, as these cells play key roles in the pathogenesis of atopic dermatitis, particularly in the chronic phase." (PMID 38541664, 2024). "As contrast, CD4+FoxP3+ Treg cells were decreased in atopic dermatitis mice, and magnolol restoration of this decrease was found." (PMID 38541664, 2024). "There was a high expression of SLC7A5 in CD4 T cells in atopic dermatitis skin with T-cell activation." (PMID 38790003, 2024). "The dermis showed an increase in the number of infiltrating CD4 T cells and a remarkable increase in toluidine blue-positive mast cells, similar to the findings in atopic dermatitis." (PMID 36983014, 2023). "Gene expression is regulated in stimulated CD4+ T cells in a disease-dependent manner in patients with atopic dermatitis (AD)." (PMID 35576187, 2022). "Specifically, it has also been observed that while perforin was increased in the skin of patients with contact dermatitis and those with atopic dermatitis, it was expressed in both CD4+ and CD8+ T cells." (PMID 36400912, 2022). "The immune responses of atopic dermatitis are a complex interplay between CD4 + T-cell activation and differentiation, the Th1/Th17 immune pathway, and mainly type 2 skewed immune dysregulation." (PMID 36476273, 2022).
atopic dermatitis (continued). "It is worth mentioning that previous studies showed that RA inhibited the IL-4 and IFN-γ expression activated CD4+ T cells and de-creased immune cell infiltration in atopic dermatitis skin lesions in mice." (PMID 33986690, 2021). "Mucosal‐associated invariant T cells, recirculating memory CD8+, and CD49+CD4+ T cells play a role in atopic dermatitis." (PMID 33135337, 2020). "Staphylococcus aureus colonizes the skin of atopic dermatitis (AD) individuals, but the impact of its enterotoxins on the chronic activation of CD4+ T cells demands further analysis." (PMID 31511620, 2019). "Here we show that CD4+ T cells from DOCK8-deficient mice produce large amounts of IL-31, a major pruritogen associated with atopic dermatitis." (PMID 28067314, 2017). "Remarkably, it has been demonstrated in a mouse model of atopic dermatitis that administration of the ω-3 fatty acid docosahexaenoic acid upregulates the generation of TGF-β-dependent CD4+ Foxp3+ Tregs." (PMID 27175277, 2016). "Pustule formation and dermal infiltration of mast cells, eosinophils and CD4+ T cells are hallmarks of the acute phase of atopic dermatitis in humans." (PMID 24843010, 2014). "This study investigated the influence of 0.00584% hydrocortisone aceponate spray (HCA; Cortavance Virbac SA, Carros, France) on blood serum cortisol levels and peripheral blood CCR4+ CD4+ T-lymphocyte levels in dogs with atopic dermatitis." (PMID 26464935, 2014). "The lack of late phase allergic symptoms due to allergen-specific T cells (e.g., atopic dermatitis) in the studied patients indeed indicates that the activity of allergen-specific CD4 cells was compromised." (PMID 24896832, 2014). "Because WT mice were able to limit skin inflammation in the atopic dermatitis model more effectively than Pglyrp3−/− and Pglyrp4−/− mice, we then tested whether this difference is due to impaired generation or function of regulatory T cells (CD4+FoxP3+ Treg) in Pglyrp-deficient mice." (PMID 21949809, 2011). "Pglyrp3−/− mice in the atopic dermatitis model also had significantly lower numbers of CD4+FoxP3+ Treg cells in the affected skin compared to WT mice measured by flow cytometry." (PMID 21949809, 2011). "A study of CD4+ T cells from atopic dermatitis patients with IgE antibody to the cat allergen Fel d 1 used tetramer binding to show a similar result, with most of the T cells being within the central memory compartment." (PMID 23282404, 2008). "In addition, CD4+ T and dendritic cells were more abundant in the atopic dermatitis samples, consistent with the immunopathology of the disease." (PMID 41556698, 2026). "Atopic dermatitis whole genome association study and downstream analysis suggest that the expression signals of CCDC80 overlap significantly in enhancers of skin cells and immune cells, particularly CD4 T cells." (PMID 38872096, 2024). "CD4+ T cells have also been used to model atopic dermatitis." (PMID 38136325, 2023). "In human clinical trials, intramuscular administration of autologous total IgG significantly increased the percentage of IL-10-producing CD4+ Treg cells in the peripheral blood of healthy subjects and provided significant clinical improvements in patients with atopic dermatitis." (PMID 38094290, 2023). "Additionally, mouse models show that the activation of IL-22 results in atopic dermatitis through an increased presence of CD4+ and CD8+ T cells, which induce inflammation." (PMID 38067173, 2023). "Experimental overexpression of TSLP in keratinocytes or intradermal injections of this cytokine, by acting on DCs and other mechanisms, result in the development of atopic dermatitis in mice, infiltration of Th2 differentiated CD4+ cells, and systemic Th2 inflammatory responses." (PMID 34571811, 2021).
atopic dermatitis (continued). "Additionally, a probiotic blend of B. lactis UABla‐12 and L. acidophilus DDS‐1, resulted in improved atopic dermatitis scoring in young children, with modulation of blood lymphocyte subsets (i.e., CD4, CD8 and CD25) suggested as a potential mechanism." (PMID 33584665, 2020). "This corresponds to inflammatory cells in the skin lesions from patients with atopic dermatitis where a significantly greater number of infiltrating CD4+ lymphocytes compared with CD8+ subtypes is reported with CD4+ ⁄CD8+ ratios similar to peripheral blood levels." (PMID 28797273, 2017). "Flea allergic dermatitis is a CD4+ T cell-mediated allergic reaction to flea allergen." (PMID 21542943, 2011). "Furthermore, RTX therapy could improve cutaneous lesions in atopic eczema patients through reducing IL-5 mRNA expression and IL-5-expressing CD4+ T-cell numbers in the skin, lowering Th2 frequencies and eosinophil counts in the blood." (PMID 34640595, 2021). "In addition, it would be interesting to investigate the S. aureus-specific CD4+ Tsrm response in patients with atopic dermatitis, a chronic and relapsing inflammatory skin disorder associated with skin barrier impairment and the predominant S. aureus colonization." (PMID 33796109, 2021). "In allergic dermatitis models, neutrophils exacerbate inflammation via LTB4‐mediated CD4+ T cell recruitment and IL‐4/IL‐13 upregulation." (PMID 41583119, 2026). "In a study of clinical human AD (Atopic Dermatitis) patients, eosinophil count correlated with the frequency of circulating TSLPR+ CD4+ T-cells." (PMID 39911485, 2024). "In humans and mice, effector T-cells, including CD4 and CD8 T cells, are pivotal in pruritic behavior, especially in atopic dermatitis (AD)." (PMID 39911485, 2024). "Rosmarinic acid inhibits production of IFN-γ and IL-4 from activated CD4+ cells, reduces the infiltration of CD4+, CD8+, and mast cells, slowing down the development of mouse atopic dermatitis." (PMID 38975345, 2024). "In fact, atopic dermatitis patients possess circulating CD4+ T cells expressing high TSLPR levels, and the frequency of this subset correlates with the severity of atopic dermatitis." (PMID 35432341, 2022). "In atopic dermatitis, immunoreactivity for PCAP receptors was observed in blood vessels, keratinocytes, mast cells and CD4+ T cells." (PMID 35387041, 2021). "The reason for this phenomenon seems to be that the previously reported anti-allergic effect such as inhibiting IL-4 and CD4+ of SCRT and its ingredients affected the progression and remission of atopic dermatitis." (PMID 33324225, 2020). "A DNCB-induced increase in CD4+RORγt+ Th17 cell fraction was reversed by DEX administration in the atopic dermatitis model but not a decrease in CD4+FoxP3+ Treg cell fraction." (PMID 38541664, 2024). "Previous histopathological examination of lesional and non-lesional skin from cats with allergic dermatitis, as well as skin from non-pruritic controls, revealed an immune cell infiltration of CD4+ and CD8+ T-cells in the skin." (PMID 39911485, 2024). "In atopic dermatitis (AD), a chronic inflammatory skin disease, characterized by eczematous skin lesions, intense pruritus, epidermal barrier defects, and by a dysregulation of the immune system, an increase of GZMB expression in CD4+ and CD8+ T cells was observed." (PMID 37470818, 2023). "A stronger link of TSLP and disease can be found in patients with atopic dermatitis with an increase of TSLP level and increased frequency of human CD4+Th2 memory cells expressing the prostaglandin D2 receptor (CRTH2), suggesting TSLP may be involved in maintenance of Th2 memory pools." (PMID 23437132, 2013). "Given that flea allergic dermatitis is a disease driven primarily by effector CD4+ T cells, our observation that the CD25- iTreg cells are effective at suppressing this disease suggests that these cells function, at least partly, by suppressing effector CD4+ T cells." (PMID 21542943, 2011).
atopic dermatitis (continued). "Studies of atopic dermatitis showed that HDM extract stimulated more of the regulatory cell transcription factor FOXP3 from PBMCs from HDM-allergic subjects than PBMCs from nonallergic subjects, and that pollen-allergic children have increased numbers of CD4+ CD25+ cells." (PMID 23282404, 2008).